ELANE (elastase, neutrophil expressed)
Diseases named in the same sentence as ELANE in open-access papers (continued):
Sharing a sentence is not in itself a finding about the gene and the disease.
tumor (continued). "It has been demonstrated that ELANE proteolysis releases the CD95 death domain, which interacts with the histone H1 subtype to selectively kill tumor cells." (PMID 40963981, 2025). "Differential expression analysis revealed that CASP4, CHMP4B, ELANE, IL-1A, and TNF were significantly upregulated in tumor samples (p < 0.05)." (PMID 40538398, 2025). "(D) Heatmaps showing expression of ICAM1 and ICAM-1 cleavage related proteases MMP9, ELANE, CTSG, ADAM10, and ADAM17 in normal or tumor tissue of 22 different cancer types." (PMID 37732732, 2023). "Seven pyroptosis-related genes (ELANE, IL18, CHMP2B, CHMP4C, CASP9, CHMP6, and CHMP2A) were downregulated in tumor tissues, while 31 pyroptosis-related genes were upregulated in tumor tissues." (PMID 35432539, 2022). "Three genes (ELANE, NLRP7, and CASP5) were downregulated, whereas seven others (GSDMC, IL1A, NOD2, GZMB, GSDMA, IL1B, and PLCG1) were overrepresented in the tumour group." (PMID 35087586, 2022). "We found that cisplatin-pretreated tumor cells stimulate neutrophils which expressed higher levels of cytotoxic effectors, including TNF-α, GZMB, and ELANE, and pro-inflammatory cytokines, such as CCL2, CCL3, CXCL10, CXCL11, and IL12." (PMID 35784745, 2022). "In total, 5 of the 34 pyroptosis-related genes were related to prognosis and four of them (ELANE, GPX4, GSDMD, and TIRAP) had different expression values between tumor and normal tissues, which were, thus, chosen as prognostic DEPRGs." (PMID 34722500, 2021). "Neutrophil elastase (ELANE), secreted into the tumor microenvironment primarily by immune cells like neutrophils and macrophages, has been shown to be upregulated in cancer." (PMID 33802262, 2021). "Neutrophil elastase (NE or ELANE) as well as matrix metallopeptidase (MMP) was shown to infiltrate the TME and promote tumor growth and invasion of cancer cells through the PIK3 signaling pathways." (PMID 33596197, 2021). "ELANE selectively kills different types of tumor cells with minimal toxicity to non-cancer cells, which increases the possibility of developing it as a broad anti-cancer therapy." (PMID 39925807, 2025). "Conversely, protein levels of these enzymes (e.g. FASN, DPP4, PREP, ELANE) showed only weak or no changes between tumors and nontumor adjacent-tissues, resulting in substantially less accurate tumor classification (right)." (PMID 40425563, 2025). "Moreover, IHC staining of the tumor tissues derived from shNKX2‐1/LL2 cells orthotopically implanted into mouse lungs also showed elevated expression of ITGAM, CEACAM8, ELANE, and CXCR2 as compared to the control." (PMID 39113226, 2024). "In the same way, α-lactalbumin (α-LA)-modified exosomes delivered the immunogenic cell death inducers human neutrophil elastase (ELANE) and Hiltonol (TLR3 agonist) to TNBC and resulted in enhanced CD8 T-cell responses in a mouse xenograft model and patient-derived tumor organoids." (PMID 36744207, 2022). "Additionally, ELANE has been shown to upregulate γ-H2AX, a robust biomarker of DNA damage, thereby linking its activity to the induction of mitochondrial dysfunction and further amplification of apoptotic signaling in tumor cells." (PMID 40748972, 2025). "This may indicate that ELANE plays a negative role in the development of tumors, which may be related to the malignancy and prognosis of the tumor." (PMID 37596368, 2023). "Elastase is generally accepted to be more pro-tumor, although there is recent evidence that human (but not murine) neutrophils release catalytically active neutrophil elastase (ELANE) capable of killing many cancer cell types with minimal toxicity to non-cancer cells." (PMID 35269405, 2022). "N1 neutrophils could directly play an anti-tumor role by modulating the expression levels of cytotoxic effectors, including tumor necrosis factor-α (TNF-α), granzyme B (GZMB), and elastase (ELANE)." (PMID 35784745, 2022).
cancer (158 papers, 2002 to 2026). A tumor composed of atypical neoplastic, often pleomorphic cells that invade other tissues. "ELANE, also known as neutrophil elastase, is a serine protease integral to immune defense and has been implicated in numerous inflammatory disorders and cancers." (PMID 40895144, 2025). "Neutrophil elastase (NE) is a protease encoded by the ELANE gene with an established protumorigenic role in various cancer types." (PMID 35011582, 2021). "Elevated ELANE levels are often linked to poor cancer prognosis." (PMID 40895144, 2025). "Furthermore, in the high-risk group, AFP, CST6, CGB5, and ELANE were significantly expressed, indicating their potential roles as cancer-promoting genes in the development of STAD." (PMID 37377916, 2023). "Its 10 variations exhibit divergent protease interactions: GzmA‐cleaved GSDMB induces pyroptotic cell death in cancer cells, whereas neutrophil elastase (ELANE) cleaved GSDMB lacks pyroptotic activity." (PMID 41574659, 2026). "KEGG pathway analysis showed significant enrichment of ELANE in pathways such as neutrophil extracellular trap formation and transcriptional misregulation in cancer." (PMID 40073065, 2025). "Neutrophil elastase (ELANE) is a potent anti‐cancer protein that kills cancer cells with multiple genes." (PMID 41369182, 2025). "Studies have found that neutrophils exert anti-cancer effects by releasing ELANE, which selectively triggers cancer cell apoptosis and supports CD8+ T cell-mediated destruction of distant metastasis." (PMID 39925807, 2025). "For example, ELANE (Neutrophil elastase), is released catalytically from neutrophils to kill many cancer cell types." (PMID 38554776, 2024). "Human neutrophils have been identified as releasing ELANE, which can selectively target and destroy a wide range of cancer cells." (PMID 38722401, 2024). "made an intriguing discovery demonstrating that human NE (or, ELANE) has the ability to selectively kill a variety of cancer cells while sparing neighboring non‐cancer cells." (PMID 38062888, 2023). "The neutrophil elastase (ELANE) is another extracellular protein released by human polymorphonuclear cells that can directly kill cancer cells." (PMID 35664746, 2022). "We found that pyroptosis genes exhibited complex methylation patterns in the 14 types of cancers, and only ELANE showed hypermethylation in 12 types of cancers." (PMID 35246158, 2022). "Studies revealed that ELANE kills cancer cells using diverse genes, but has the least toxicity to non-cancer cells." (PMID 35296025, 2022). "ELANE was significantly downregulated in almost all cancers but obviously upregulated in GBM (log2FC = 2.07) and LAML (FC = 12.15)." (PMID 35246158, 2022). "Future studies aimed at the mechanism by which histone H1 and CD95-DD complexes trigger apoptosis will shed more light on the cancer-selective property of ELANE." (PMID 34599140, 2021). "Taken together, these results strongly suggest that histone H1 isoforms play an essential role in ELANE’s selective toxicity against cancer cells." (PMID 34599140, 2021). "LGALS1 and BCL2A1 may play roles in promoting cancer in AML, while ELANE may have a significant effect on suppressing cancer." (PMID 38205232, 2024). "Deserving attention is the cancer-selective property of ELANE." (PMID 34599140, 2021). "Interestingly, neutrophils may also release catalytically active neutrophil elastase (ELANE) to kill many cancer cell types while sparing non-cancer cells." (PMID 37097516, 2023). "The new studies identify an accomplice role for the interaction between TPM2 and ELANE in promoting LUAD progression and provide potential strategies in the prevention and/or treatment of LUAD and other cancers." (PMID 40199876, 2025). "Neutrophil elastase (ELANE), a key antitumor effector in activated neutrophils, is functionally mimicked by porcine pancreatic elastase (PPE), which exhibits selective cancer cytotoxicity." (PMID 40585978, 2025).
cancer (continued). "A recent study demonstrated that human neutrophils release catalytically active neutrophil elastase (ELANE), which proteolytically cleaves the CD95 death domain, binding it to histone H1 in cancer cells." (PMID 38474175, 2024). "Protein kinase CAMP-activated catalytic subunit alpha (PRKACA), elastase neutrophil expressed (ELANE), NLRP1, pejvakin (PJVK), and CASP9 were significantly downregulated in 25, 24, 22, 25, and 23 types of cancers, respectively." (PMID 35246158, 2022). "PRTN3, ELANE, CTSG and MMP9 are the serine proteases released by the activated neutrophils and have been reported to degrade ECM proteins and promote cancer cell invasion." (PMID 36686780, 2022). "Several proteins involved in carcinogenesis or leukemogenesis are increased for clinical responders (ANO6, CHI3L1, CTSG, ELANE and FGR), suggesting that the sensitivity to ATRA/VP additionally depends on more general functions involved in cancer development." (PMID 33946813, 2021). "Interestingly, certain repressed genes like B4GALT2, ELANE, CTSG, MLC1, NMP3, and SLC43A3 act as cancer suppressors, inhibiting malignant features and cancer development." (PMID 40986633, 2025). "The neutrophil degranulation complex was defined by the terms antimicrobial peptides (R-HAS-6803157), neutrophil degranulation (R-HSA-6798695), response to yeast (GO:0001878), and transcriptional misregulation in cancer (KEGG:05202); it included the proteins ELANE, H3-5, MPO, LYZ, and PRTN3." (PMID 39997396, 2025). "Firstly, they can release catalytically active neutrophil elastase (ELANE), which can kill various cancer cell types while sparing non-cancer cells." (PMID 38512527, 2024). "We found that the expression of the ELANE (elastase) gene, which has been reported to have an anti-cancer function in human neutrophils, was negative in all neutrophils." (PMID 36869384, 2023). "The results show that expression of ELANE, PRKACA, CASP3, CASP9 and CASP6 was related to the efficacy of various anticancer drugs, indicating that pyroptosis genes may participate in pan‐cancer signalling pathways and affect the efficacy of anticancer drugs." (PMID 34816605, 2022). "ELANE selectively kills a broad range of cancer cells and exhibits minimal toxicity to noncancer cells." (PMID 35148751, 2022). "We observed that NLRP7 (n = 8), AIM2 (n = 10), CASP8 (n = 6), GSDMA (n = 5), GSDMB (n = 8), and GSDMC (n = 12) mainly showed hypomethylation in most cancers, and PLCG1 (n = 11), NLRP6 (n = 13), ELANE (n = 11), CASP6 (n = 5), NLRC4 (n = 12), and PYCARD (n = 8) showed hypermethylation in most cancers." (PMID 35246158, 2022). "While human neutrophils release a catalytically active ELANE, instead murine neutrophils do not and hence fail to kill cancer cells, both in vivo and in vitro." (PMID 35664746, 2022). "Notably, neutrophil elastase (ELANE) expression selectively targets cancer cells without harming normal cells." (PMID 38474175, 2024). "Moreover, ELANE is a serine protease released by human neutrophils that selectively kills cancer cells and has no toxicity to normal cells." (PMID 35148751, 2022). "This invention showed that ELANE, identified as the major anticancer protein released by PMNs, could cleave the CD95 receptor, releasing an intracellular proteolytic fragment containing the Death Domain and selectively killing a wide range of cancer cells." (PMID 35301281, 2022). "Intriguingly, ELANE can not only selectively induce cell death in diverse cancer cells, but not in normal cells, through liberating the CD95 death domain (DD) that interacts with histone H1 isoforms, but also prevent distant metastasis through triggering an abscopal effect mediated by CD8+ T cells." (PMID 34599140, 2021).
infection (129 papers, 2005 to 2025). The state of being infected such as from the introduction of a foreign agent such as serum, vaccine, antigenic substance or organism. "The ELANE gene encodes for a protein that is found in neutrophils and plays a role in inflammation and in fighting infection." (PMID 33664235, 2021). "In addition to CD11b, several proteins are known to be strongly expressed by neutrophils, such as myeloperoxidase (MPO), the antimicrobial protein lipocalin (LCN2), neutrophil gelatinase-associated lipocalin (NGAL), and neutrophil elastase (ELANE), were strongly enriched in AM upon infection." (PMID 37790937, 2023). "The ELANE gene regulates the synthesis of neutrophil elastase, which is secreted by neutrophils to fight infection when the body produces an immune response to fight infection." (PMID 41369182, 2025). "Significant changes in the expression of PRTN3, MPO, and ELANE proteins are very important in the early stage of infection and are significantly related to the severity of the disease." (PMID 37904697, 2023). "The levels of MPO and ELANE in the liver were raised rapidly upon infection both in the parenchyma and vascular proteomes, whereas their deposition in the cardiac parenchyma and vasculature was first observed after 12 h." (PMID 35913192, 2022). "These include three proteases that are upregulated during the course of infection: the matrix metalloprotease MMP9, the serine proteases neutrophil elastase (ELANE), and cathepsin G (CTSG), as well as the protease inhibitor SERPINB1." (PMID 23638192, 2013). "In summary, ELANE and LCN2 were enriched in neutrophil activation and correlated with infection and septic shock, especially ELANE as the only prognostic gene could participate through NETs formation and pyroptosis pathways." (PMID 36911395, 2023). "Statistically significant protein alterations of PRTN3, MPO, ELANE, CTSG, and AZU1 dysregulation is important in the early phases of infection and may be targets for anti-SARS-CoV-2 therapeutics." (PMID 33079950, 2020). "The identified up-regulated proteins Myeloperoxidase, Myeloblastin, Neutrophil Elastase, Cathepsin G, and Azurocidin (MPO, PRTN3, ELANE, CTSG, and AZU1) in naso-oropharyngeal swab samples are discussed to highlight the molecular mechanism changes in the site of infection." (PMID 33079950, 2020). "Furthermore, the hypomethylation found in the gene coding for neutrophil elastase (ELANE) and proteinase 3 (PRTN3) may alter the formation of NETs (neutrophil extracellular traps), which is an earlier mechanism used by neutrophils to fight infection." (PMID 33659006, 2021). "None of the major neutrophil effector molecules Elastase (ELANE), Proteinase 3 (PRTN3), Cathepsin G (CTSG) and Myeloperoxidase (MPO) changed significantly in response to infection." (PMID 38472281, 2024).
bacterial infection (26 papers, 2011 to 2025). "ELANE gene-related SCN is rare in children, and the possibility of this disease should be considered in children with recurrent severe bacterial infections and a significant reduction in neutrophils in the peripheral blood shortly after birth." (PMID 36343040, 2022). "The expression of ELANE, MPO and CD177 was not influenced by sex or the presence of bacterial infection." (PMID 34552111, 2021).
inflammation (11 papers, 2011 to 2025). Aberrant reaction of the microcirculation characterized by movement of fluid and leukocytes from the blood into extravascular tissues. "Here, we show a possible pathomechanism between ELANE mutation, diminished NE and SLPI expression, and dental inflammation in ELANE dental pulp cells." (PMID 34580954, 2021).
neurodegenerative disease (2 papers, 2018 to 2024). A disorder of the central nervous system characterized by gradual and progressive loss of neural tissue and neurologic function.
ELANE also shares sentences with these, for which no sentence is quoted: lung disease (43 papers); chronic obstructive pulmonary disease (38); bronchiectasis (36); pulmonary fibrosis (27); respiratory diseases (10); type 2 diabetes (10); Stroke (9); myocardial infarction (8); acute lung injury (7); liver fibrosis (7); pneumococcal pneumonia (7); prostate carcinoma (7); systemic inflammatory response syndrome (7); fatty liver disease (6); injury (6); vasculitis (6); cardiovascular disease (5); glioma (5); ischemic stroke (5); peritonitis (5); acute pancreatitis (4); chronic bronchitis (4); endometritis (4); preeclampsia (4); pulmonary edema (4); retinopathy (4); septic shock (4); type 1 diabetes (4); allergic asthma (3); allergic disease (3).
A further 231 diseases each share a sentence with ELANE in 3 papers or fewer.